TCEAL1 (transcription elongation factor A like 1)
Description:
May be involved in transcriptional regulation. Modulates various viral and cellular promoters in a promoter context-dependent manner. For example, transcription from the FOS promoter is increased, while Rous sarcoma virus (RSV) long terminal repeat (LTR) promoter activity is repressed. Does not bind DNA directly.
Synonyms: SIIR; p21; pp21; WEX9; HIJRS; NEDGFAX
Tractability: PROTAC: ubiquitination databases record sites on it.
Gene: Protein-coding gene on chromosome X (103,628,701 to 103,630,958, forward strand). Ensembl gene ENSG00000172465.
Subcellular location: Nucleus
Subcellular location (Human Protein Atlas): Nucleoplasm
Gene Ontology:
Molecular function: protein binding
Biological process: negative regulation of gene expression
Cellular component: nucleoplasm; nucleus
Homologues: Orthologues: chimpanzee TCEAL1 (99% identical), macaque TCEAL1 (99% identical), dog TCEAL1 (90% identical), rabbit TCEAL1 (87% identical), pig TCEAL1 (86% identical), mouse Tceal1 (84% identical), rat Tceal1 (81% identical). Paralogues in human: TCEAL8 (31% identical), TCEAL9 (30% identical), TCEAL2 (24% identical), TCEAL7 (24% identical), TCEAL5 (23% identical), TCEAL4 (23% identical), TCEAL3 (22% identical), TCEAL6 (21% identical).
Diseases named in the same sentence as TCEAL1 in open-access papers:
TCEAL1 is named in the same sentence as 12 diseases in open-access papers, as found by Europe PMC text mining. Sharing a sentence is not in itself a finding about the gene and the disease. The quoted sentences say what the papers report.
prostate carcinoma (3 papers, 2020 to 2023). A carcinoma that arises from epithelial cells of the prostate gland. "For the first time, TCEAL1 is implicated in enhancing docetaxel anti-cancer effects in prostate cancer." (PMID 33033111, 2020). "Tceal1 was the gene with the most significant negatively selected sgRNAs, sensitising all prostate cancer cell lines tested to docetaxel, and given its putative role in transcription, we chose TCEAL1 as our top target for further study." (PMID 33033111, 2020). "Here, we report the first in vivo genome-wide treatment sensitisation CRISPR screen in prostate cancer, and present proof of concept data on TCEAL1 as a candidate for a combinational strategy with the use of docetaxel." (PMID 33033111, 2020). "Collectively, our whole genome in vivo CRISPR screen has identified TCEAL1 as a potential target to sensitise prostate cancer cells to docetaxel." (PMID 33033111, 2020). "In future studies, it would therefore be pertinent to test if suppression of TCEAL1 expression also sensitises prostate cancer cells to cabazitaxel treatment." (PMID 33033111, 2020). "Focussing on Tceal1 as the top hit, LNCaP, DU145, and CWR22 human prostate cancer cell lines were also sensitised to docetaxel treatment upon suppressed TCEAL1 expression." (PMID 33033111, 2020). "A whole genome in vivo CRISPR/Cas9 screen identifies TCEAL1 as a potential target to sensitise prostate cancer cells to docetaxel to improve the efficacy of chemotherapy." (PMID 33033111, 2020). "Suppressed TCEAL1 expression in multiple human prostate cancer cell lines enhanced therapeutic response to docetaxel." (PMID 33033111, 2020). "Therefore, silencing the TCEAL1 expression improves docetaxel efficacy in prostate cancer treatment." (PMID 36969009, 2023). "We successfully validated the top target TCEAL1 in both murine and human prostate cancer cells." (PMID 33033111, 2020).
breast carcinoma (1 paper, 2020). "In addition, overexpression of the ESPL1 separase protease (another E2F target gene) was observed upon TCEAL1 knockdown; ESPL1 is implicated to increase aneuploidy in a murine breast cancer model." (PMID 33033111, 2020).
esophageal squamous cell carcinoma (1 paper, 2013). Esophageal squamous cell carcinoma (ESCC) is a type of esophageal carcinoma (EC) that can affect any part of the esophagus, but is usually located in the upper or middle third. "Microarray study showed that the expression of TCEAL1 was markedly decreased in esophageal squamous cell carcinoma samples compared to matched normal samples." (PMID 23372750, 2013).
gastric cancer (1 paper, 2013). A primary or metastatic malignant neoplasm involving the stomach. "The TCEAL7 expression level was significantly lower in the gastric cancer cell lines comparing with the levels of TCEAL1, TCEAL3, TCEAL4, TCEAL5 and TCEAL8." (PMID 23372750, 2013). "A real-time quantitative PCR was performed on normal gastricepithelial cell line GES1 and gastric cancer cell lines including AGS, MKN45, MGC803, SGC7901 and HGC27 to determine the mRNA levels of TCEAL1, TCEAL3, TCEAL4, TCEAL5, TCEAL7 and TCEAL8." (PMID 23372750, 2013).
metastatic prostate carcinoma (1 paper, 2020). A carcinoma that arises from the prostate gland and has spread to other anatomic sites. "In addition, because docetaxel is often combined with ADT as an upfront treatment for routine management of metastatic prostate cancer, future studies to test the value of TCEAL1 in the context of combined chemo-hormonal therapy are necessary." (PMID 33033111, 2020).
Noonan syndrome (1 paper, 2016). Noonan Syndrome (NS) is characterized by short stature, typical facial dysmorphism and congenital heart defects. "It is interesting to note that TCEAL1 has been shown to interact with PTPN11, the causative gene for Noonan syndrome characterized by short stature, craniofacial anomalies, pectus deformities, webbed neck and sometimes ID." (PMID 27506666, 2016).
serous ovarian cancer (1 paper, 2020). "Whereas TCEAL2 up-regulation was reported to associate with poor prognosis for serous ovarian cancer patients, TCEAL-1, 4, and 7 were reported to be down-regulated in different tumour types." (PMID 33033111, 2020).
cancer (3 papers, 2009 to 2020). A tumor composed of atypical neoplastic, often pleomorphic cells that invade other tissues. "Sensitising cancer cells to docetaxel by targeting TCEAL1-mediated mechanism could therefore have wider implications for cancer therapy." (PMID 33033111, 2020). "It is reported that TCEAL1 was involved in the apoptosis of human cancer cells." (PMID 23372750, 2013).
neurodevelopmental disorder (1 paper, 2024). A behavioral and cognitive disorder with onset during the developmental period that involves impaired or aberrant development of intellectual, motor, or social functions. "One such example is deletion at Xq22.2, previously associated with a neurodevelopmental disorder which has more recently been found to be caused by de novo loss-of-function variants in TCEAL1." (PMID 38200082, 2024).
tumour (1 paper, 2020). "Future in vivo studies would focus on tumour response to treatment and further work would be warranted to decipher the mechanism by which TCEAL1 regulates the cell cycle, thus allowing the development of a more precise approach for combination treatment with docetaxel." (PMID 33033111, 2020).
TCEAL1 also shares sentences with these, for which no sentence is quoted: colorectal cancer (1 paper); neurological disease (1).